IL10 (interleukin 10)
Diseases named in the same sentence as IL10 in open-access papers (continued):
Sharing a sentence is not in itself a finding about the gene and the disease.
colitis (continued). "Our hypothesis was that one TNBS dose could induce acute onset of colitis and the acute inflammation could be sustained and progress to chronic colitis in IL-10-/- mice." (PMID 31534535, 2019). "However, after treatment with SASP and IN, the levels of IL-6, IL-8, and TNF-α decreased greatly compared with the colitis group, while the levels of IL-10 increased." (PMID 31726738, 2019). "In line with this, increased levels of IL-10 in combination with a reduction of IL-9, which is associated with intestinal barrier disruption, have been reported upon treatment with adenovirally delivered VEGF-C in mice undergoing DSS-induced colitis." (PMID 30863410, 2019). "Lactobacillus salivarius Ls33 rescued mice from colitis in an IL10-dependent manner." (PMID 30696799, 2019). "Moreover, B cells in the mLNs of mice with DSS-induced colitis had a markedly lower expression level of Rbm47 and IL-10." (PMID 29844590, 2019). "Our study in Il10-/- mice demonstrated that the oligosaccharide 2FL specifically promoted the expansion of the Lachnospiraceae R. gnavus, thereby decreasing the development of colitis in young animals after weaning." (PMID 31275292, 2019). "For instance, Bifidobacterium-induced IL-10 production benefits patients with colitis." (PMID 31681193, 2019). "Although the mechanisms by which PI3Kδ dysfunction induces colitis remain unclear, reduced IL-10 production by bacteria-stimulated macrophages and regulatory T cells potentially contribute to induce colitis in PI3Kδ mutant mice." (PMID 31546615, 2019). "We demonstrated that Gls1 inhibition by BPTES ameliorated colitis in IL‐10−/− mice, as shown by histopathology and by reductions in inflammation scores and the DAI, which was associated with significantly decreased Th1 and Th17 responses but increased Treg responses." (PMID 31211512, 2019). "The replacement of E. faecalis wild type strain by a Δeut mutant resulted in exacerbated colitis in SIHUMI colonized IL-10−/− mice, as indicated by increased histological inflammation, increased tissue expression of TNF and IL-12p40 and increased spleen weights." (PMID 31281321, 2019). "Another experimental approach to achieving loss of IL-10 function, thus making mice prone to developing microbiota-dependent colitis, is the use of mice lacking the IL-10 gene." (PMID 31827095, 2019). "In addition, weight loss in mice with colitis that were treated with M2 macrophage exosomes (DSS + M0-exo; DSS + IL-13-exo; DSS + IL-10-exo; and DSS + IL-1β-exo) was also alleviated." (PMID 31749791, 2019). "Additionally, the negative correlation of intestinal VDR expression and ATG16L1 is found in UC patients as well as IL-10−/− mice with colitis." (PMID 31847438, 2019). "At first, the Il10−/− model of spontaneous colitis was applied." (PMID 30315190, 2018). "It has also been shown that miR-155 may aggravate colitis by directly inhibiting Th17 cell differentiation in CD4+ T cells or by regulating IL-10-producing B cells." (PMID 29774026, 2018). "It was recently reported that B. fragilis protects against DSS-induced colitis in germfree mice by inducing IL-10 expression, suggesting that B. fragilis helps to prevent intestinal diseases in both the presence and the absence of microbiota, using different molecular mechanisms." (PMID 30429227, 2018). "Indeed, infection with H. diminuta has been repeatedly shown to inhibit DNBS-induced inflammation in mice, whereas B cells, alternatively activated macrophages and IL-10 have all been shown to have the potential to mediate the suppression of colitis." (PMID 30341242, 2018). "Moreover, IL-9 secreted by iNKT cells in the DSS-mediated colitis model also dampened the immune response by inducing the release of IL-10 and TGF-β (anti-inflammatory cytokines)." (PMID 29881387, 2018). "Indeed, oral feeding butyrate promoted intestinal T-cell IL-10 production and inhibited colitis development upon DSS insults, further supporting for SCFAs as therapeutic target in treatment of IBD." (PMID 30177845, 2018).
colitis (continued). "Colitis can also be prevented by regulating IL-10 expression." (PMID 30289911, 2018). "Th17 cells express IL-10Rα and IL-10 signalling has been shown to control IL-17A producing CD4+ T cells in a colitis model, suggesting that IL-10 may be an important regulator of IL-23/Th17 responses during anti-fungal immunity." (PMID 29793796, 2018). "However, despite this apparently pro-inflammatory mechanism of action, administration of AsnRS in the mouse T cell transfer model of colitis induces regulatory responses and induction of IL-10." (PMID 30462997, 2018). "An in vivo study furthermore indicated that the administration of chemerin resulted in aggravation of DSS-induced colitis in mice by augmenting TNFα and IL-6 production, whereas a decrease in IL-10—producing anti-inflammatory macrophages could be detected." (PMID 30369924, 2018). "Unexpectedly, transfer of splenic IL-10-producing Foxp3neg CD4+ T cells caused colitis upon transfer, while small intestinal IL-10-producing Foxp3neg CD4+ T cells did not cause colitis as expected." (PMID 30575716, 2018). "Consequently, any impairment of the IL10/IL10-R axis, leading to a deficit in IL10 production or signaling, promotes the early onset of colitis in humans." (PMID 29799517, 2018). "We observed that neither gene (IL-10 or Foxp3) was induced by B. fragilis during colitis-associated CRC." (PMID 30429227, 2018). "Mirroring this improvement in colitis, Rag2−/−hLrh1IEC-TG animals showed a decreased inflammatory cytokine profile, with lower intestinal expression of TNFα, IL-1β, and IL-6, and a corresponding increase in the anti-inflammatory cytokine IL-10." (PMID 30305617, 2018). "ODNs given therapeutically after colitis has developed worsen disease whereas when given prophylactically there is a reduction in inflammation thought possible due to a tolerance effects on IFNγ or on increasing IL-10 production." (PMID 29515999, 2018). "Similarly, western blotting and immunohistochemical staining showed decreased expression of Erbin, increased expression of LC3B, decreased expressions of ATG16L1 and ATG2A in DSS-induced colitis mice and IL-10-/- mice compared with that in control mice." (PMID 29552291, 2018). "Because our mouse model leads to transcription of the IL-10 transgene in the bone marrow and elevated seric IL-10 concentration, we investigated whether IL-10 could imprint immune cells in a long-lasting way, thus conferring sustained protection to colitis." (PMID 29545807, 2018). "A decrease in the abundance of B cells producing IL-10 (Breg cells) has been observed in patients with CD, and adoptive transfer of IL-10-producing B cells ameliorates intestinal inflammation in a mouse model of colitis." (PMID 30083167, 2018). "It relies on several mechanisms of suppression, but IL-10 is fundamental during colitis." (PMID 30575716, 2018). "In vitro experiments indicated that IL-10 production by intestinal immune cells might be critically involved in the tolerogenic mechanisms triggered by therapeutic FMT during experimental colitis." (PMID 30518790, 2018). "Moreover, to determine if our methodology contributes to robust therapeutic value, candidate compounds require validation in multiple models (e.g., DSS-induced colitis, CD4+ T-cell adoptive transfer colitis, and IL-10 KO)." (PMID 30300381, 2018). "Thus, despite the protection afforded by IL-10 in colitis, novel strategies are required, specifically to achieve long-lasting protection." (PMID 29545807, 2018). "Indeed, M2-associated genes (Arg1, IL-10, Fizz1, and Mrc1) were increased and M1-associated genes (IL-1β, IL-6, IL-12, and TNF-α) were decreased in colons of DSS colitis miR-155−/− mice." (PMID 29774026, 2018). "However, after treatment with sulfasalazine and TRYP, the levels of IL-6 and TNF-α decreased greatly comparing with the colitis group, while the levels of IL-1β and IL-10 changed insignificantly." (PMID 29724065, 2018).
colitis (continued). "In addition, the abrogation of colitis in IL-10−/− mice with the deletion of CXCL10 further emphasized its role in IBD47." (PMID 29720595, 2018). "Further supporting our results, several studies have recently reported increased severity of colonic inflammation not only in models of chemically induced colitis, but also in IL-10 KO mice, which spontaneously develop colitis, and in Salmonella typhimurium infected mice, while on HSD." (PMID 29566748, 2018). "IL-10 maintains the expression of Foxp3 on Tregs, an important source of IL-10 in colitis mice." (PMID 29784012, 2018). "The company’s ambition is strongly based on the landmark study that demonstrated that chemically induced colitis in mice could be effectively treated with L. lactis strains that produce interleukin-10 (IL-10)." (PMID 30123213, 2018). "Pretreatments with TGF-β- and IL-10-neutralizing antibodies reversed the ameliorated colitis pathology and the upregulation of Treg/Th17 ratio after H. pylori stimulation further proved this hypothesis." (PMID 30237392, 2018). "Indeed, indiscriminate inhibition of COX enzymatic activity with piroxicam accelerates colitis in both IL10−/− mice and during transfer of CD4+ cells from IL10−/− mice into Rag1/− mice." (PMID 30619314, 2018). "Development of colitis is often associated with chronic inflammation, characterized by inflammatory cellular infiltration and series of cytokines secretion, such as TNF-α, IFN-γ, IL-6, IL-1β, IL-4, and IL-10." (PMID 29538417, 2018). "The administration of IL-33 accelerated spontaneous colitis in IL-10-deficient mice but did not induce intestinal inflammation in wild-type mice." (PMID 29922293, 2018). "We found that induction of IL-10 prior to DSS administration impacted the progression of colitis." (PMID 29545807, 2018). "We investigated the impact of IL-10 overexpression prior to DSS-induced colitis." (PMID 29545807, 2018). "The experiments on a murine model with acute chemical-induced inflammation showed that both F. prausnitzii cells and supernatant reduced the severity of acute colitis and induced increased secretion of anti-inflammatory IL-10 and decreased secretion of proinflammatory cytokines." (PMID 30060606, 2018). "The answer may lie in the fact that IL-10 has been shown to be important for maintenance of Foxp3 expression and regulatory cell suppressor function in colitis." (PMID 30455704, 2018). "As noted, IL-10 has been closely linked to both GI dilatation and MHV-68 infection and IL-10-deficient (knock-out) mice display GI dilatation with spontaneous colitis." (PMID 30249047, 2018). "Finally, we evaluated the therapeutic potential of cell specific expression of the anti-inflammatory IL10 cytokine in Ly6c+ inflammatory leukocytes in a dextran sodium sulfate (DSS) colitis model." (PMID 30374059, 2018). "To understand how the expansion of the myeloid compartment might contribute to the colitis in Il10−/− hosts, we examined the cytokine secretion profile of CD11b+ cells from uninfected and H. hepaticus-infected Il10−/− mice." (PMID 29203542, 2018). "Thus, our data showed that IL-10 overexpression prior to intestinal insult afforded a significant degree of protection from DSS-induced colitis." (PMID 29545807, 2018). "Oral delivery of recombinant IL-27 food-grade bacterium Lactococcus lactis ameliorates the murine colitis in a T cell-dependent colitis model, including improving survival, decreasing clinical score and pathologic score, downregulating inflammatory cytokines, and increasing IL-10." (PMID 28420941, 2017). "Since Hsp65-LL maintained the physiological levels of IL-10, we investigated whether the prevention of colitis by Hsp65-L." (PMID 28194152, 2017). "This is supported by a study demonstrating that an avirulent strain of Salmonella, incapable of inciting inflammation, could only colonize the murine intestine in induced- colitis models or IL-10 knock-out mice." (PMID 29121673, 2017).
colitis (continued). "The importance of IL-10 in modulating T-cell responses was further demonstrated in an interesting study where a recombinant B. longum NCC2705, producing human IL-10 from a plasmid, was shown to ameliorate colitis in mice by increasing Treg cells and decreasing Th17 cells." (PMID 33525778, 2017). "It was reported that, the strain Lactobacillus subspecies could reduce mucosal permeability, prevent colitis onset, and alleviate inflammatory reaction in IL-10-/- mice." (PMID 29113344, 2017). "In another mouse colitis model using IL-10−/− mice which develop spontaneous chronic colitis within 18 weeks, resveratrol was able to induce immunosuppressive CD11b+ Gr-1+ MDSCs in the colon and suggests an as-yet-unidentified mode of anti-inflammatory action of this plant polyphenol." (PMID 28465680, 2017). "Restricting IL-10 deficiency to myeloid cells does not cause colitis which confirms that macrophages are not the main source of protective IL-10 in this model." (PMID 28316998, 2017). "It was demonstrated that oral administration of Bifidobacterium could block intestinal inflammation by acting on Tr1 cells, leading to the production of IL-10, thereby ameliorating colitis in immunocompromised mice." (PMID 29234327, 2017). "Previous studies have shown that IL-6 and IL-10 play essential roles for the maintenance of intestinal homeostasis and the prevention of colitis, while proinflammatory cytokines, such as IL-17 and IL-15 promote intestinal dysbiosis associated with increased susceptibility to colitis." (PMID 28943876, 2017). "Likewise, neonatal maternal separation stress enhances the permeability of the colonic mucosa both in wildtype and IL-10−/− mice, but colitis develops only in IL-10−/− mice, which attests to the multifactorial pathogenesis of chronic GI inflammation." (PMID 29213271, 2017). "IL‐10 secretion was dramatically reduced in DP1‐deficient myeloid cells in DSS‐induced colitis mice, strongly indicating that the niacin/GPR109A axis‐mediated anti‐inflammatory IL‐10 secretion may depend on PGD2/DP1 signaling in myeloid cells." (PMID 28341703, 2017). "When mice were fed a LF diet supplemented with taurocholic acid, but not with glycocholic acid, development of colitis were observed in IL-10-deficient mice." (PMID 28294972, 2017). "Conflicting reports have been published on the effect of experimental colitis on IL-10 levels." (PMID 28769047, 2017). "Reduces DSS-induced colitis by induction of IL-10 production by macrophages." (PMID 29163443, 2017). "To investigate how F991 reduced DSS-induced colitis, we used ELISA to analyze the levels of proinflammatory cytokines, including IL-6 and TNF-α, and the levels of the anti-inflammatory cytokine IL-10 in cultured supernatant from DSS-colitis tissues after F991 treatment on the 2nd, 4th, 6th days." (PMID 28701727, 2017). "To further validate the miRNA signature, we lessened the degree of colitis in IL10−/− mice and investigated whether it reflected the treatment of colitis by returning to the non-colitic signature." (PMID 28566745, 2017). "Interesting mechanistic studies in this system have shown that protection required established infection, as STAT6-deficient mice both cleared the parasite and developed severe colitis; moreover, protection by infection was abolished by anti-IL-10 blocking antibodies." (PMID 28302598, 2017). "In contrast, the incidence of colitis in IL-10-deficient mice fed PUFA was no different than those fed LF." (PMID 28294972, 2017). "Interestingly, LL-anti-mTNF-α also shows some effects on disease severity in established colitis in IL10−/− mice." (PMID 29387056, 2017). "The data indicate that the anti-colitis effect of Turkish galls might be mediated by Treg cells induction and consequent increase in IL-10 in the colon." (PMID 28446747, 2017).
colitis (continued). "Additionally, it was shown that GH boosts epithelial proliferation and has a beneficial effect on colonic histopathology scores in spontaneous colitis in IL-10 knock out (k.o.)mice." (PMID 28946616, 2017). "IL-10 produced by macrophages could however partly contribute to colitis protection, as it triggers Treg cell protection when anticommensal T cells are adoptively transferred into a sensitive host." (PMID 28316998, 2017). "However, the protective effects against colitis were higher in mice treated with recombinant probiotics expressing elafin than those treated with probiotics expressing IL-10." (PMID 28491143, 2017). "This prompted us to study gastrointestinal colonization properties and potential TLR4 dependent intestinal as well as extra-intestinal immune responses upon MDR PA challenge under chronic intestinal inflammatory conditions applying the chronic IL10−/− colitis mouse model." (PMID 29151895, 2017). "This latter finding shows that disease pattern in non-colitic IL10−/− mice (i.e., at an age before the development of colitis) behave differently from non-genetically susceptible WT mice." (PMID 28566745, 2017). "MF did not affect the onset and incidence of colitis in wild type mice, but increased onset and incidence in IL-10-deficient mice, driving it from a spontaneous rate of 25%–30% (on LF) to over 60% in a 6-month period." (PMID 28294972, 2017). "A previous work has presented that consumption of milk-derived fat not only promoted the expansion of B. wadsworthia in SPF mice, but also increased incidence of colitis in colon of genetically susceptible Il10−/− mice, while not in wild-type mice." (PMID 29090023, 2017). "Administration of everolimus to IL-10-deficent mice, which develops spontaneous colitis, inhibits the proliferation of activated T cells, decreases the number of Th1 cells and the production of inflammatory cytokines by Th1 cells in the lamina propria, and ultimately ameliorates chronic colitis." (PMID 29209321, 2017). "To confirm the involvement of IL-10 in the anti-colitogenic activity of Hsp65-LL, we tested whether the spontaneous colitis developed in IL-10−/− mice could be ameliorated by the Hsp65-L." (PMID 28194152, 2017). "For example, in dextran sulfate sodium- (DSS-) induced colitis in mice, both oral and dietary administration of resveratrol caused reductions of proinflammatory cytokines, TNF-α, IFN-γ, IL-8, and IL-1β, and an increase of the anti-inflammatory cytokine IL-10." (PMID 28465680, 2017). "Furthermore, the H. polygyrus-mediated alleviation of colitis in the RAG IL-10−/− T cell transfer colitis was observed, when H. polygyrus infected mice were dewormed before T cell transfer colitis." (PMID 28938014, 2017). "Furthermore, the protein levels of TNF-α and IL-10 also exhibited a similar pattern in samples from the colitis mice." (PMID 28701721, 2017). "Interestingly, C. jejuni induced colitis was more pronounced in NOD2−/− IL-10−/− mice as compared to IL-10−/− mice." (PMID 28127403, 2017). "Besides, butyrate suppresses the production of proinflammatory cytokines, enhances anti-inflammatory IL-10 expression, and activates regulatory T cells (Treg cells), leading to the amelioration of colitis." (PMID 28536285, 2017). "For example, in a mouse model of experimental colitis, the concentration of butyrate was significantly increased in the lumen of colons that contained a greater abundance of IL-10+Foxp3+ cells, resulting in amelioration of colitis in mice fed with butyrate-supplemented diet." (PMID 28763485, 2017). "It appeared that the purified B. fragilis PSA was sufficient to act on host analogous to the live bacterium, including the initiation of IL-10 production by Tregs, suppression of Th17 cell production, disease protection from colitis, and colonization of the host." (PMID 28061847, 2017).